EZR (ezrin)
Diseases named in the same sentence as EZR in open-access papers (continued):
Sharing a sentence is not in itself a finding about the gene and the disease.
tumor (continued). "Our data indicate that the chemosensitizing effect of anti-ezrin therapy largely affects disseminated cancer cells at their secondary organ site, as no significant changes in primary tumor regression or CTC levels were observed with the addition of NSC to DOX or DTX treatment." (PMID 36923551, 2022). "This may help explain why anti-ezrin treatment in our preclinical models specifically sensitizes metastatic, and not primary tumor cells, to chemotherapy drugs." (PMID 36923551, 2022). "Distant metastasis was not also related to the positive expression of KIF14 and Mieap and negative expression of EZR in other morphological arrangements of tumor cells: tubular, alveolar, solid and trabecular structures and small groups of tumor cells (data not shown)." (PMID 32679794, 2020). "In addition, SNAIL was identified as a crucial factor involved in PI3K-AKT signaling and the EZRIN-RHO pathway that may be regulated by SDF-1 and HGF, factors that promote tumor cell metastasis." (PMID 32664538, 2020). "This subset of proteins was particularly enriched in proteins involved in tumor metastasis and malignancy, such as proteins from the canonical actin cytoskeleton signaling, including several members of the RhoA/RhoGDI signaling pathway (ACTR2, EZR, MSM, PFN, GDI2)." (PMID 29872504, 2018). "They hypothesized that the intensity rather than the pattern of ezrin expression had a more probable impact on the tumor behavior but admitted that larger studies are needed for clarification." (PMID 27578920, 2016). "The tumor-free survival rates were significantly higher for patients with GCTB at Campanacci stages I and II than for those with GCTB at Campanacci stage III (P < 0.01) while the tumor-free survival rate was obviously lower for ezrin (+ +) GCTB patients than for ezrin (−/+) GCTB patients (P < 0.01)." (PMID 25929323, 2015). "Additionally, the expression status of ezrin, ezrinThr-567 and ezrinTyr-353 proteins was not correlated with age, gender or tumor size of patients with NSCLC." (PMID 24629131, 2014). "The aim of this work was to investigate maspin and ezrin expression in periocular BCC to throw light on their role in pathogenesis of this carcinoma by immunohistochemistry, together with correlating their expression with the clinicopathological features of the tumor." (PMID 25580109, 2014). "In the present study, we found that p-ezrin exhibited cytosolic and membranous staining patterns in NSCLC, and the percentages of ezrinThr-567 and ezrinTyr-353 expression were significantly higher in NSCLC than in adjacent non-tumor tissues and normal tissue counterparts (P < 0.01)." (PMID 24629131, 2014). "However, the rates of positive ezrin, ezrinThr-567 and ezrinTyr-353 expression were significantly higher in NSCLC than in the adjacent non-tumor tissues and normal lung tissue counterparts, with rates of 62.7%, 63.3% and 71.3% in NSCLC, respectively (P < 0.01)." (PMID 24629131, 2014). "EZR is overexpressed in many cancers, including PDAC, even in PanIN lesions, and it interacts with cortactin to form podosomal rosettes in PDAC cells, which may play an important role in tumor invasion." (PMID 24010981, 2013). "The mechanism by which pY477 ezrin regulates tumor invasion in AC2M2 cells is not known." (PMID 22397367, 2012). "In contrast, the majority of mice injected with tumour cells overexpressing amino-terminal ezrin (NTC6, NTC7, NTB8) showed no metastatic lesions; the few metastases that did form (in the NTC7 group) were generally smaller and primarily localized to vascular channels." (PMID 15987432, 2005). "In addition, six genes, KRT18, ARPC5L, ACTG1, ARPC2, EZR, and YWHAZ, were simultaneously enriched in tumors and tumor tissues highly expressing TNFRSF11B, which may enhance pathogenic E. coli focal adhesion, actin filament binding, and cadherin binding, as demonstrated by GO functional analysis." (PMID 34938284, 2021).
tumor (continued). "At the same time, based on Ezrin phosphorylation observed in response to CXCL16 in PC3, it could be inferred that CXCR6-CXCL16 interaction may cause cytoskeleton rearrangement and promote tumor cell metastasis independent of androgen." (PMID 26799186, 2016). "Thus, we analyzed the expression and localization of ezrin/p-ezrin in NSCLC compared with the normal counterparts, determined its relationship with clinicopathological parameters, and investigated its prognostic value for NSCLC patients based on tumor stage and survival data." (PMID 24629131, 2014). "In human samples, Spearman correlation analysis based on Clinical Proteomic Tumor Analysis Consortium (CPTAC) also revealed a negative correlation between TRIM59 expression and phosphorylation of ezrin (R = −0.23)." (PMID 30408026, 2018). "Overexpression of EZR, CLIC5 and PODXL genes was observed in nodular (N) and tumor (T) areas but not in non-tumor (NT) areas and controls (C)." (PMID 26135398, 2015). "Furthermore, 12-O-tetradecanoylphorbol-13-acetate (TPA), a tumor promoter, could lead to the malignant transformation of human embryonic esophageal mucosa cells to ESCC cells, in which ezrin was overexpressed obviously, suggesting TPA might be an inducer of VIL2 overexpression in ESCC cells." (PMID 25915860, 2015). "Interestingly, although Erk1/2 activation is also reduced in amino-terminal ezrin-expressing cells, inhibition of the MAPK pathway has no detectable effect on cell motility or invasion in this tumour model." (PMID 15987432, 2005). "Another importance is that gene silencing of ezrin, but not of radixin and moesin significantly decreased the cell surface expression of P-gp without affecting the levels of the ABCB1 mRNA in LS180 cells cultured at the acidic pH condition which mimics the actual tumor microenvironment." (PMID 33974673, 2021).
cancer (231 papers, 2005 to 2026). A tumor composed of atypical neoplastic, often pleomorphic cells that invade other tissues. "The EZR gene encodes ezrin, which is highly activated and upregulated in cancer cells, contributing to their invasive potential." (PMID 41029807, 2025). "Ezrin functions as a critical linker between the actin cytoskeleton and the plasma membrane and is involved in multiple cancer-associated signaling pathways." (PMID 41029807, 2025). "As the fine-tune balance of mitochondrial dynamicity is associated with cancer and neurodegenerative diseases, our findings highlight the potential relevance of Ezrin in tuning the mitochondrial activity in cell homeostasis and survival." (PMID 41145430, 2025). "Given the aberrant expression and modification of ACAP4 and ezrin in cancer pathogenesis, we further investigated the mechanism underlying ACAP4-mediated cancer cell invasion and migration." (PMID 40082743, 2025). "High EZRIN expression level has been extensively studied and often associated with metastasis and cancer progression." (PMID 41145430, 2025). "Ezrin (encoded by the EZR gene) is a highly expressed protein in cancer that contributes to linking the actin cytoskeleton to the cell membrane and signal transduction pathways involved in oncogenesis and disease progression." (PMID 38972247, 2024). "The cytoskeletal protein ezrin is upregulated in many cancer types and is strongly associated with poor patient outcome." (PMID 36938826, 2023). "There is a large amount of evidence that has shown that ezrin expression is associated with enhanced cellular motility and invasion, as well as metastasis and poor prognosis for cancer patients." (PMID 36899847, 2023). "The PPI network analysis in STRING indicated the interconnection of ezrin with CD44, which is congruent with literature data reporting that ezrin binds to cell-adhesion molecule CD44 implicated in cancer-cell migration and metastasis." (PMID 37629086, 2023). "Elevated levels of ezrin are considered to be an important step towards carcinogenesis, with increased levels seen in numerous cancers and its expression linked to the metastasis of numerous solid tumours." (PMID 36899847, 2023). "Aberrant EZR expression is associated with poor prognosis and metastasis in various cancers including PDAC." (PMID 37171030, 2023). "The selected pG4-BS include sequences from various gene segments of cancer-associated genes, such as EZR, PRN1, RARA and NF1." (PMID 37094040, 2023). "High levels of Ezrin were found to be associated with metastatic behavior in various types of cancer." (PMID 37947661, 2023). "Accordingly, pre-clinical and clinical studies designed to explore the benefits of combined BRAF inhibitors and drugs targeting the ezrin-regulated actin cytoskeleton as a novel therapeutic approach for BRAFV600E-mutated cancers should be encouraged." (PMID 37629086, 2023). "The overexpression of ezrin is significantly associated with poor clinical outcomes in many cancers." (PMID 36077137, 2022). "In support of that inference, other studies have linked ezrin to the survival of newly disseminated cancer cells at distant organ sites through these same pathways." (PMID 36923551, 2022). "Because of this, ezrin is implicated as a regulator of cancer metastasis, playing critical roles in cancer cell migration and invasion." (PMID 36923551, 2022). "Specifically, the expression of ezrin was associated with epithelial cells (i.e., carcinoma cells), compared to the mesenchymal expression of vimentin (i.e., stroma cells/fibers)." (PMID 34198671, 2021). "It is interesting to note that the Ezrin expression was associated with bad prognosis in a cancer type-specific manner." (PMID 33240887, 2020). "Emerging evidence has demonstrated that Ezrin is an oncogene protein, as high levels of Ezrin are associated with metastatic behavior in various types of cancer." (PMID 33240887, 2020).
cancer (continued). "Although Ezrin is known associated with poor prognosis in several cancers, the predictive value of Ezrin and its relationships with clinicopathological features or prognostic parameters remain controversial." (PMID 33240887, 2020). "Several clinical studies have linked high expression of ezrin or phosphorylation of ezrin at threonine T567 with poor outcomes in patients suffering from a wide variety of cancers." (PMID 31936668, 2020). "Collectively, our results suggest that ezrin’s phosphorylation state plays a pivotal role in cells’ biophysical behaviors that are typically associated with metastasis and cancer progression." (PMID 31936668, 2020). "This is consistent with previous studies showing that the invasive and metastatic ability of cancer cells is linked to high expression of phosphorylated ezrin." (PMID 31936668, 2020). "Elevated ezrin expression and abnormal cytoplasmic localization are associated with aggressive cancers, and positively associated with a degree of malignancy and poor prognosis in several cancer types." (PMID 33086476, 2020). "A highly metastatic variant of murine OSA cells is enriched for ezrin and in vivo mouse models demonstrated that ezrin promotes a survival effect upon cancer cell’s arrival to the lung, possibly through the activation of MAPK signalling." (PMID 33066583, 2020). "The effect of ezrin targeted therapy in reducing cancer cell motility, together with the clinical association of ezrin with increased risk of relapse, points to ezrin as an important regulator of the metastatic process in BC." (PMID 30678714, 2019). "In summary, our meta-analysis has demonstrated that the high Ezrin expression is significantly associated with poor survival in cancer patients." (PMID 26632332, 2015). "To resolve the conflicting issues, we performed a systematic review and meta-analysis on the association between Ezrin expression and prognostic value in cancer patients." (PMID 26632332, 2015). "Drosophila So has not been shown to control the expression of cytoskeleton component genes, but the murine So homolog Six1 directly activates Vil2, which encodes the actin cytoskeleton regulator Ezrin, thus promoting cell motility and metastasis in cancer." (PMID 24586968, 2014). "Earlier reports showed that highly invasive FLSs obtained from PIA-susceptible DA (blood type D, Agouti) rats have increased expression of genes associated with invasive cancers, including Villin-2/ezrin." (PMID 24688409, 2014). "Furthermore, cancer cell proliferation and invasion through an activated Akt/mTORC1 pathway was linked with activation of Ezrin." (PMID 39937579, 2025). "Further, Ezrin is up-regulated in various cancers and associated with poor prognosis." (PMID 37791063, 2023). "Ezrin is upregulated in various cancers and is associated with a poor prognosis." (PMID 34485151, 2021). "Elevated ezrin expression in several cancers is associated with poor outcomes." (PMID 33086476, 2020). "EZR overexpression causes the increased invasion of cancer cells." (PMID 33033380, 2020). "Ezrin, which is known as a cytoskeleton linker protein, is closely linked with the metastatic progression of cancer and is frequently abnormally expressed in aggressive cancer types." (PMID 30804430, 2019). "Activation of Ezrin and NF-κB is associated with cancer metastasis and poor patient prognosis." (PMID 30995931, 2019). "The association between elevated ezrin expression and increased risk of metastases in node-positive BC prompted us to investigate the effect of pharmacological inhibition of ezrin to restrain cancer cell migration in vivo." (PMID 30678714, 2019). "Ezrin is overexpressed in several kinds of cancers, which is associated with adverse outcomes." (PMID 28298808, 2017).
cancer (continued). "Several cell membrane and cytoskeleton-related proteins are overexpressed in many types of cancers, including Ezrin (EZR) and Podocalyxin (PODXL), which are associated with morphogenesis and migration because they function as scaffold proteins between the cell membrane and actin cytoskeleton." (PMID 26135398, 2015). "Furthermore, cathepsin D and ezrin are secreted aberrantly and excessively in various types of cancers, and are associated with increased cancer growth, invasion, and metastasis." (PMID 23389041, 2013). "We further show that overexpression of wild-type ezrin increases carcinoma cell invasion, whereas amino-terminal ezrin causes reduced cell scattering, motility and invasion, thus indicating a possible mechanism by which ezrin regulates progression to invasive cancer." (PMID 15987432, 2005). "Podocalyxin (PODXL), a protein overexpressed in many aggressive cancers, links the cell membrane to the internal skeleton through its interaction with Ezrin, an actin cytoskeleton cross-linker." (PMID 41718268, 2026). "Phactr4 deletions and ezrin activation have been noted in several cancers, including breast, colorectal, lung, ovarian, and renal tumors." (PMID 40462895, 2025). "Recently, several attempts have been made to develop therapeutic pharmacological approaches to treat cancers in which Ezrin is overexpressed and sustain tumors growth and metastasis." (PMID 41145430, 2025). "RhoA and Ezrin are recognized proto-oncogenes, frequently overexpressed in various cancer types, which further underscored their potential importance in the context of miR-183 regulation." (PMID 40630207, 2025). "Through direct inhibition of ezrin, miR-138 remodels the cytoskeleton, reducing cancer cells’ capacity to generate migratory and invasive structures like filopodia and lamellipodia." (PMID 40723199, 2025). "These include cancer relevant loci near the S100 family of genes, which are considered prognostic markers for patients with colorectal neoplasia, and EZR, a known mediator of invasion and metastasis." (PMID 40343989, 2025). "Disruptions in EZR function can lead to spindle misorientation, with significant implications for cancer progression and developmental biology." (PMID 40366509, 2025). "Enhanced motility, invasiveness, and poor clinical outcomes are commonly linked to altered expression of ABPs, including cofilin, fascin, profilin, gelsolin, and ezrin, which are often dysregulated in malignancies." (PMID 40723199, 2025). "Increasing attention has been given to the functional characterization of the ezrin protein and its relationship with different types of cancer." (PMID 38972247, 2024). "In the present study, the authors examined EZR mRNA levels across various cancers through a comprehensive pan-cancer analysis." (PMID 38972247, 2024). "Ezrin is an androgen-regulated gene and has been suggested as a target for cancer diagnosis and therapy due to its involvement in cancer progression, metastasis, and patient survival cancers." (PMID 39858418, 2024). "Reported evidence has indicated the facilitation of cancer cell migration and invasion through the regulation of Ezrin activation by DSG3 (23752190)." (PMID 38900156, 2024). "All in all, these data indicate that both ezrin and its phosphorylated form play important roles in motility and invasion in line with work carried out in cancer cells where the relocalisation of ezrin in membrane and microvilli also improved these properties." (PMID 36899847, 2023). "Selective ezrin inhibitor NSC305787 is an experimental anti-cancer agent that has been so far evaluated only in pre-clinical studies which showed that NSC305787 has acceptable toxicity and pharmacokinetics profiles in murine models." (PMID 37629086, 2023). "Ezrin has an important role in maintenance of protein structural stability and integrity, and can promote cancer occurrence and progression." (PMID 37791063, 2023).